FANCD2 (FA complementation group D2)
Diseases named in the same sentence as FANCD2 in open-access papers (continued):
Sharing a sentence is not in itself a finding about the gene and the disease.
Hepatitis B- (1 paper, 2023). "High FANCD2 expression was associated with poor prognosis in Hepatitis B-related HCC and was shown to be an independent prognostic factor by multivariate Cox analysis." (PMID 37821996, 2023). "FANCD2 is associated with multiple pathways, including DNA repair and tumor proliferation signatures, in Hepatitis B-related HCC." (PMID 37821996, 2023). "Our study reveals that FANCD2 is significantly upregulated in Hepatitis B-related HCC and is a promising diagnostic and prognostic biomarker." (PMID 37821996, 2023). "Our study showed that the expression of FANCD2 was increased and that high FANCD2 expression was associated with poor outcomes and unfavorable immune infiltration in Hepatitis B-related HCC." (PMID 37821996, 2023). "FANCD2 may be involved in hepatocyte injury caused by Hepatitis B." (PMID 37821996, 2023). "The higher the expression of FANCD2, the stronger the tumor dryness index of Hepatitis B-related HCC (P = 1.59e−07; P = 0.42; 95% CI, [0.27, 0.55])." (PMID 37821996, 2023). "In this study, we investigated the prognostic significance and mechanism of action of FANCD2 in Hepatitis B-related HCC." (PMID 37821996, 2023). "Our results indicated that FANCD2 was significantly overexpressed in Hepatitis B-related HCC and demonstrated a strong predictive ability for diagnosis (Area Under Curve, 0.903) and prognosis of the disease." (PMID 37821996, 2023). "Thus, FANCD2 could be a potential diagnostic and prognostic biomarker for Hepatitis B-related HCC." (PMID 37821996, 2023). "High FANCD2 expression was associated with poor prognosis, high-grade tumors, high expression of PDL-1, high MSI scores, and low sorafenib IC50 in Hepatitis B-related HCC." (PMID 37821996, 2023). "Using ssGSEA, the correlation between FANCD2 and this pathway was analyzed in Hepatitis B-related HCC." (PMID 37821996, 2023). "The expression of FANCD2 in Hepatitis B-related HCC was explored using The Cancer Genome Atlas (TCGA) and validated using the Gene Expression Omnibus (GEO) database." (PMID 37821996, 2023). "In this study, we analyzed the relationship between the ferroptosis-related gene FANCD2 and the development, prognosis, treatment, immunity, and other related functions of Hepatitis B-related HCC using the TCGA and GEO databases." (PMID 37821996, 2023). "Univariate and multivariate Cox regression analyses and Kaplan–Meier survival curves were used to analyze the relationship between FANCD2 expression and the overall survival of patients with Hepatitis B-related HCC." (PMID 37821996, 2023). "FANCD2 was positively correlated with MSI in Hepatitis B-related HCC (P = 0.023 and P Spearman, 0.19)." (PMID 37821996, 2023). "Furthermore, we verified that the expression of FANCD2 was higher in Hepatitis B-related HCC than in normal tissues in GSE121248 (P = 5.9e−10), GSE55092 (P = 0.0021), GSE19665 (P = 1.1e−05) and GSE84402(P = 0.00034)." (PMID 37821996, 2023). "Therefore, this study aimed to analyze the prognostic significance and mechanism of the ferroptosis-related gene FANCD2 in Hepatitis B-related HCC to predict therapeutic response." (PMID 37821996, 2023). "Our study indicated that FANCD2 was a potential novel biomarker and immunotherapeutic target against Hepatitis B-related HCC, which might be related to the chemotherapeutic response to sorafenib." (PMID 37821996, 2023). "In addition, our study demonstrated that the higher the expression of FANCD2, the stronger the stem cell characteristics of tumor cells, with lower differentiation and higher proliferative capacity in Hepatitis B-related HCC." (PMID 37821996, 2023). "Therefore, FANCD2 may affect ferroptosis by altering the iron metabolism in Hepatitis B-related HCC." (PMID 37821996, 2023). "In the (TCGA) dataset, the expression of FANCD2 in many types of cancers, including HCC and Hepatitis B-related HCC, was higher than that in normal tissues." (PMID 37821996, 2023).
Hepatitis B- (continued). "Our study revealed a negative correlation between FANCD2 expression and the IC50 value of sorafenib in Hepatitis B-related HCC, indicating that patients with higher FANCD2 expression are more likely to have a better therapeutic response to sorafenib." (PMID 37821996, 2023). "We found a positive correlation between FANCD2 expression and Tregs, B cells, CD4 + T cells, CD8 + T cells, neutrophils, and macrophage infiltration in Hepatitis B-related HCC." (PMID 37821996, 2023). "Thus, FANCD2 may serve as a novel therapeutic target for Hepatitis B-related HCC." (PMID 37821996, 2023). "In Hepatitis B-related HCC, FANCD2 expression was highest in Asian patients compared to black and white patients, according to our analysis." (PMID 37821996, 2023). "The expression level of FANCD2 significantly correlated with the infiltration levels of Treg cells, B cells, CD8 + T cells, CD4 + T cells, neutrophils, macrophages, myeloid dendritic cells, and NK cells in Hepatitis B-related HCC." (PMID 37821996, 2023). "However, there are no relevant studies on the effects of FANCD2 on Hepatitis B-related HCC." (PMID 37821996, 2023).
Hereditary breast and ovarian cancer syndrome (1 paper, 2025). An autosomal dominant inherited syndrome caused by mutations in the BRCA1 or BRCA2 genes. "The pathogenic mutations in genes such as MUTYH, FANCD2, NBN, PALB2, and BRCA1 are associated with hereditary breast and ovarian cancer syndrome, an autosomal dominant disorder typically manifesting around age 30 and above." (PMID 41229399, 2025).
hereditary cancer (1 paper, 2020). Malignant neoplasms occurring in families at a rate greater than that expected by chance and caused by germline mutations in a specific gene. "A prospective cohort of 1021 unrelated cancer cases with clinical suspicion of hereditary cancer was screened for mutations in the following 14 FA genes: FANCA, FANCB, FANCC, FANCD2, FANCE, FANCF, FANCG/XRCC9, FANCI, FANCL/PHF9, FANCM, FANCP/SLX4, FANCQ/ERCC4, FANCR/RAD51 and FANCU/XRCC2." (PMID 32235514, 2020).
high-grade glioma (1 paper, 2021). "Recently, there has been a study related to Fanconi anemia group D2 protein (FANCD2) as a modulating factor of carboplatin sensitivity in pediatric high-grade glioma (pHGG)." (PMID 34065991, 2021).
invasive breast carcinoma (1 paper, 2014). A carcinoma that infiltrates the breast parenchyma. "This may suggest that a mutation in FANCD2 predispose to invasive breast cancer of ductal type, however further studies are needed in this regard." (PMID 25093046, 2014).
liver dysfunction (1 paper, 2025). "However, Adh5-/-Fancd2-/- mice, which accumulate high levels of endogenous ICLs, do develop liver dysfunction and cancer." (PMID 40684071, 2025).
male infertility (1 paper, 2025). The inability of the male to effect fertilization of an ovum after a specified period of unprotected intercourse. "For example, the V555F variant, which causes male infertility through Sertoli only syndrome, completely lacks ATPase activity while retaining normal FANCD2:FANCI monoubiquitination stimulation." (PMID 40447800, 2025).
metastatic cancer (1 paper, 2020). A carcinoma which has spread from the original site of growth to another anatomic site. "Analysis of a few patients with metastatic cancer survive exceptionally longer than others under the same treatment identified multiple common mutations of NOTCH2, NF1, FANCD2, PIK3CB and EPHA5 in tumors that responded exceptionally well to treatments." (PMID 32600248, 2020).
metastatic tumors (1 paper, 2021). "The metastatic tumors retained most of the genetic variants found in the original tumors, but some cases had additional CNVs, including copy number gains for the KRAS, AKT3, RICTOR, FGFR, and FANCD2 genes, and copy number losses for the MYC and RAD50 genes." (PMID 34422662, 2021).
myocardial infarction (1 paper, 2024). Gross necrosis of the myocardium, as a result of interruption of the blood supply to the area, as in coronary thrombosis. "SLC2A3, EPAS1, HMOX1, ATM and FANCD2 genes all had good diagnostic value for myocardial infarction (P < 0.05)." (PMID 38253721, 2024). "The increase of SLC2A3, EPAS1 and HMOX1 were risk factors for myocardial infarction, while ATM and FANCD2 were protective factors." (PMID 38253721, 2024). "According to the method of systematic random sampling, the sample size was divided into test set and verification set, and the decision tree model of SLC2A3, EPAS1, HMOX1, ATM and FANCD2 genes on myocardial infarction was established." (PMID 38253721, 2024). "The increase of SLC2A3, EPAS1 and HMOX1 are risk factors for myocardial infarction, while ATM and FANCD2 are protective factors.Decision tree analysis showed that SLC2A3, HMOX1, ATM, FANCD2 gene had higher net yield in diagnosing myocardial infarction." (PMID 38253721, 2024). "The results showed that SLC2A3, HMOX1, ATM and FANCD2 genes had higher net yield in the diagnosis of myocardial infarction." (PMID 38253721, 2024). "ROC curves of 5 different genes related to ferroptosis associated with myocardial infarction showed that SLC2A3, EPAS1, HMOX1, ATM and FANCD2 genes had good diagnostic value for myocardial infarction, and the elevation of SLC2A3, EPAS1 and HMOX1 was a risk factor for myocardial infarction." (PMID 38253721, 2024). "ROC curves of 5 differentially ferroptosis-related genes associated with myocardial infarction showed that SLC2A3, EPAS1, HMOX1, ATM and FANCD2 genes had good diagnostic value for myocardial infarction, and the area under the curve had statistical significance (P < 0.05)." (PMID 38253721, 2024).
oligodendroglioma (1 paper, 2014). A well-differentiated (WHO grade II), diffusely infiltrating neuroglial tumor, typically located in the cerebral hemispheres. "Consistent with the overall findings in our archived tissue samples, we observed negligible FANCD2 staining in one particular low-grade (radiology diagnosis) oligodendroglioma originally diagnosed in 2011." (PMID 25071006, 2014). "FANCD2 expressing cells were never detected in schwannomas and only 7% of grade II oligodendrogliomas exhibited FANCD2 expression." (PMID 25071006, 2014).
Pancytopenia (1 paper, 2021). An abnormal reduction in numbers of all blood cell types (red blood cells, white blood cells, and platelets). "While mice with combined deficiency in ADH5 and the corresponding repair gene FANCD2 would result in blood pancytopenia, the reduction of bone marrow cellularity and the acceleration of HSC attrition cause failure to sustain hematopoiesis." (PMID 33573309, 2021).
pertussis (1 paper, 2022). A contagious bacterial respiratory infection caused by Bordetella pertussis. "Additionally, the only pathway positively correlated with FANCD2 expression was the cell cycle, as shown in the results of the KEGG pathway analysis, whereas three pathways were negatively associated with the expression of FANCD2: phagosome, pertussis, and pancreatic secretion." (PMID 36267413, 2022).
pituitary adenoma (1 paper, 2025). "Regulation of FANCD2 by the mTOR pathway, a molecular pathway known to contribute to cancer cell resistance to DNA damage also in pituitary adenoma, increases tumor cell survival." (PMID 40415137, 2025).
plasmacytoma (1 paper, 2016). Plasmacytoma is a localized mass of neoplastic monoclonal plasma cells that represents approximately 5% of all plasma cell neoplasms. "While LTBMC derived K14E7 Fancd2−/− and K14E7 Fancd2+/+ cell lines showed expression of CK14 and its linked E7 oncogene protein in both marrow stromal and hematopoietic cells, only hematopoietic cell lines from the former generated malignant plasmacytoma cell lines in vitro." (PMID 27637088, 2016). "Furthermore, cytokeratin 14 and E7 were expressed in cultured K14E7 Fancd2−/− marrow and nonadherent cells subcultured in Interleukin-3 (IL-3) generated factor-independent (FI) malignant plasmacytoma cell lines." (PMID 27637088, 2016).
rectal cancer (1 paper, 2024). A primary or metastatic malignant neoplasm that affects the rectum. "Copy number variations of core hub genes are widely present in colon and rectal cancers, with CHGA and FANCD2 primarily showing copy number heterozygous deletion, while the rest mainly exhibit copy number heterozygous amplification." (PMID 39120548, 2024).
schwannoma (1 paper, 2014). A benign, usually encapsulated slow growing tumor composed of Schwann cells. "Using both archived and fresh GBM tissue, we demonstrate that in contrast to normal brain tissue or benign Schwannomas, the key FA pathway protein FANCD2 is re-expressed and that the FA pathway is active in GBMs." (PMID 25071006, 2014).
Seckel syndrome (1 paper, 2012). A rare autosomal recessive inherited syndrome caused by mutations in the ATR gene, RBBP8 gene, CENPJ gene, CEP152 gene, CEP63 gene, NIN gene, DNA2 gene, or TRAIP gene. "For instance, ATR-mediated phosphorylation of FANCD2 is essential for its monoubiquitination in response to DNA damage as shown by absence of FANCD2 monoubiquitination in ATR-deficient cells and cells from patients with Seckel syndrome, a disease resembling FA." (PMID 22737580, 2012).
somatotropinomas (1 paper, 2025). "Consequently, these findings emphasize the ability of FANCD2 to modulate macrophage differentiation in different tumor types, thereby proposing the hypothesis that a similar phenomenon may occur in somatotropinomas." (PMID 40415137, 2025). "Among the genes included in this pathway, recent studies have suggested that FANCD2, SPTA1, TYRO3, and ZNF335 genes are emerging as key players in immune response and regulating tumorigenesis, even if their role has not been studied in TME of somatotropinomas." (PMID 40415137, 2025).
squamous cell tumors (1 paper, 2016). "K14E7 Fancd2−/− mice are known to develop squamous cell tumors of the oral cavity and the female cervix, but in this model, either oral chemical carcinogen or estrogen pellet placement respectively was also required for carcinogenesis." (PMID 27637088, 2016). "We confirmed that K14E7 Fancd2−/− mice treated with oral 4-NQO developed squamous cell tumors of the oral cavity and esophagus, but we saw no detectable effect of oral 4-NQO treatment of these tumor bearing mice on malignant transformation of their explanted bone marrow in LTBMCs." (PMID 27637088, 2016). "The K14E7 Fancd2−/−, but not K14E7 Fancd2+/+ mice in these experiments did develop oral cavity squamous cell tumors." (PMID 27637088, 2016).
squamous cervical cancer (1 paper, 2014). "Therefore, our findings demonstrate that baseline FANCD2, RAD51, BRCA1 and BRIP1 nuclear protein expression could have an important role in treatment failure in advanced squamous cervical cancer." (PMID 24708616, 2014).
thymoma (1 paper, 2022). A neoplasm arising from the epithelial cells of the thymus. "Among the 33 cancer types, ACSL4 expression was most correlated with TMB in ACC, whereas FANCD2, HIF3A, HSPA5, and PSMB7 were most correlated with TMB in thymoma (THYM)." (PMID 35652069, 2022).
uveal melanoma (1 paper, 2016). A melanoma derived from melanocytes of the uveal tract. "FANCD2 is also required for the spontaneous levels of SCEs in uveal melanoma, thus we speculate that even during unperturbed replication FANCD2 regulates the pathway choice for DSBs repair." (PMID 26765540, 2016).
virus infection (1 paper, 2026). "To confirm that deubiquitination of PCNA and FANCD2 was mediated through USP1 in virus infection, we depleted USP1 using siRNA knockdown." (PMID 41533576, 2026).
Xeroderma pigmentosum variant (1 paper, 2010). Xeroderma pigmentosum variant is a milder subtype of xeroderma pigmentosum (XP; see this term), a rare genetic photodermatosis characterized by severe sun sensitivity and an increased risk of skin cancer. "The hypersensitivity to DNA-crosslinking agents, such as UV-irradiation, inherent to cells derived from patients with FA or XPV (Xeroderma Pigmentosum Variant), or to yeast deficient in Rad6, further indicates specific links among FANCD2, pol η, and human homologs of yeast Rad6 (HHR6)." (PMID 20967207, 2010).